SLC6A4 (solute carrier family 6 member 4)
Description:
Serotonin transporter that cotransports serotonin with one Na(+) ion in exchange for one K(+) ion and possibly one proton in an overall electroneutral transport cycle. Transports serotonin across the plasma membrane from the extracellular compartment to the cytosol thus limiting serotonin intercellular signaling. Essential for serotonin homeostasis in the central nervous system. In the developing somatosensory cortex, acts in glutamatergic neurons to control serotonin uptake and its trophic functions accounting for proper spatial organization of cortical neurons and elaboration of sensory circuits. In the mature cortex, acts primarily in brainstem raphe neurons to mediate serotonin uptake from the synaptic cleft back into the pre-synaptic terminal thus terminating serotonin signaling at the synapse (By similarity). Modulates mucosal serotonin levels in the gastrointestinal tract through uptake and clearance of serotonin in enterocytes. Required for enteric neurogenesis and gastrointestinal reflexes (By similarity). Regulates blood serotonin levels by ensuring rapid high affinity uptake of serotonin from plasma to platelets, where it is further stored in dense granules via vesicular monoamine transporters and then released upon stimulation. Mechanistically, the transport cycle starts with an outward-open conformation having Na1(+) and Cl(-) sites occupied. The binding of a second extracellular Na2(+) ion and serotonin substrate leads to structural changes to outward-occluded to inward-occluded to inward-open, where the Na2(+) ion and serotonin are released into the cytosol. Binding of intracellular K(+) ion induces conformational transitions to inward-occluded to outward-open and completes the cycle by releasing K(+) possibly together with a proton bound to Asp-98 into the extracellular compartment. Na1(+) and Cl(-) ions remain bound throughout the transport cycle. Additionally, displays serotonin-induced channel-like conductance for monovalent cations, mainly Na(+) ions. The channel activity is uncoupled from the transport cycle and may contribute to the membrane resting potential or excitability (By similarity).
Synonyms: SERT; 5HTT; HTT; 5-HTT; SERT1; 5-HTTLPR; OCD1; hSERT
Tractability: Small molecule: an approved drug acts on it; a structure with a bound ligand is known; a high-quality ligand is known; it belongs to a druggable protein family. Antibody: UniProt places it where antibodies can reach, with high confidence; its Gene Ontology location is reachable by antibodies, with high confidence; UniProt predicts a signal peptide or a membrane-spanning region. PROTAC: a small molecule that binds it is known. Other modalities: a drug acting on it is in phase 2 or 3 trials.
Target class: SLC superfamily of solute carriers; SLC06 neurotransmitter transporter family; Electrochemical transporter; Transporter
Chemical probes: CITALOPRAM (high quality), escitalopram (high quality)
Safety:
Unwanted effects reported when the protein is acted on. In parentheses: how it was acted on, where the effect was seen, and who reports it.
sexual dysfunction (Urban et al. (2012): inhibition, cardiovascular system, nervous system, gastrointestinal; Bowes et al. (2012): inhibition, cardiovascular system, central nervous system; ClinPGx)
anxiety (Urban et al. (2012): inhibition, cardiovascular system, nervous system, gastrointestinal; Bowes et al. (2012): inhibition, cardiovascular system, central nervous system)
diarrhea (Lynch et al. (2017): inhibition, acute dosing, central nervous system, cardiovascular, gastrointestinal, blood; Urban et al. (2012): inhibition, cardiovascular system, nervous system, gastrointestinal)
headache (Urban et al. (2012): inhibition, cardiovascular system, nervous system, gastrointestinal; Lynch et al. (2017): inhibition, acute dosing, central nervous system, cardiovascular, gastrointestinal, blood)
insomnia (Urban et al. (2012): inhibition, cardiovascular system, nervous system, gastrointestinal; Bowes et al. (2012): inhibition, cardiovascular system, central nervous system)
nausea (Lynch et al. (2017): inhibition, acute dosing, central nervous system, cardiovascular, gastrointestinal, blood; Bowes et al. (2012): inhibition, cardiovascular system, central nervous system)
Decrease, Population growth rate (inhibition; source: AOP-Wiki)
Increased, Population (inhibition; source: AOP-Wiki)
agitation (inhibition, acute dosing; central nervous system, cardiovascular, gastrointestinal, blood; source: Lynch et al. (2017))
constipation (inhibition, acute dosing; central nervous system, cardiovascular, gastrointestinal, blood; source: Lynch et al. (2017))
decreased appetite (inhibition, acute dosing; central nervous system, cardiovascular, gastrointestinal, blood; source: Lynch et al. (2017))
decreased body weight (inhibition, acute dosing; central nervous system, cardiovascular, gastrointestinal, blood; source: Lynch et al. (2017))
decreased eating (inhibition, acute dosing; central nervous system, cardiovascular, gastrointestinal, blood; source: Lynch et al. (2017))
decreased plasma renin (inhibition; cardiovascular system, central nervous system; source: Bowes et al. (2012))
decreased platelet aggregation (inhibition, acute dosing; central nervous system, cardiovascular, gastrointestinal, blood; source: Lynch et al. (2017))
decreased sleep (inhibition, acute dosing; central nervous system, cardiovascular, gastrointestinal, blood; source: Lynch et al. (2017))
decreased upper gastrointestinal transit (inhibition; cardiovascular system, central nervous system; source: Bowes et al. (2012))
Decreased, Reproductive Success (inhibition; source: AOP-Wiki)
decreased/increased anxiety (inhibition, acute dosing; central nervous system, cardiovascular, gastrointestinal, blood; source: Lynch et al. (2017))
decreased/increased locomotor activity (inhibition, acute dosing; central nervous system, cardiovascular, gastrointestinal, blood; source: Lynch et al. (2017))
dizziness (inhibition, acute dosing; central nervous system, cardiovascular, gastrointestinal, blood; source: Lynch et al. (2017))
dry mouth (inhibition, acute dosing; central nervous system, cardiovascular, gastrointestinal, blood; source: Lynch et al. (2017))
gastrointestinal cramps (inhibition; cardiovascular system, nervous system, gastrointestinal; source: Urban et al. (2012))
Increase, predation (inhibition; source: AOP-Wiki)
increased gastrointestinal motility (inhibition; cardiovascular system, central nervous system; source: Bowes et al. (2012))
increased other serotonin-mediated effects (inhibition; cardiovascular system, central nervous system; source: Bowes et al. (2012))
Increased, predation (inhibition; source: AOP-Wiki)
Increased, Reproductive Success (inhibition; source: AOP-Wiki)
nausea and vomiting (inhibition; cardiovascular system, nervous system, gastrointestinal; source: Urban et al. (2012))
primary pulmonary hypertension (inhibition; cardiovascular system, nervous system, gastrointestinal; source: Urban et al. (2012))
and 9 more effects
Gene: Protein-coding gene on chromosome 17 (30,194,312 to 30,238,482, reverse strand). Ensembl gene ENSG00000108576.
Subcellular location: Cell membrane; Endomembrane system; Endosome membrane; Synapse; Cell junction, focal adhesion; Cell projection, neuron projection
Subcellular location (Human Protein Atlas): Golgi apparatus; Vesicles
Pathways (Reactome):
Neuronal System: Serotonin clearance from the synaptic cleft
Transport of small molecules: SLC-mediated transport of neurotransmitters
Gene Ontology:
Molecular function: antiporter activity; integrin binding; monoamine transmembrane transporter activity; protein binding; serotonin binding; serotonin:sodium:chloride symporter activity; sodium ion binding; actin filament binding; identical protein binding; monoatomic cation channel activity; neurotransmitter transmembrane transporter activity; cocaine binding; nitric-oxide synthase binding
Biological process: regulation of thalamus size; response to toxic substance; serotonin uptake; amino acid transport; membrane depolarization; neurotransmitter transport; platelet aggregation; sodium ion transmembrane transport; behavioral response to cocaine; brain morphogenesis; cellular response to cGMP; cellular response to retinoic acid; circadian rhythm; conditioned place preference; enteric nervous system development; locomotory behavior; male mating behavior; memory; negative regulation of cerebellar granule cell precursor proliferation; negative regulation of neuron differentiation; negative regulation of organ growth; negative regulation of synaptic transmission, dopaminergic; neurotransmitter reuptake; positive regulation of cell cycle; positive regulation of gene expression; and 8 more
Cellular component: endomembrane system; endosome membrane; Golgi apparatus; membrane raft; plasma membrane; focal adhesion; neuron projection; synapse; membrane; postsynaptic membrane; presynaptic membrane; serotonergic synapse
Genetic constraint (gnomAD): Loss-of-function variants: 18 observed, 63.4 expected, observed/expected ratio (o/e) 0.28, 90% interval 0.19 to 0.42. The upper end of that interval is the gene's LOEUF score, 0.42, which puts it in group 1 of 6, group 1 being the genes least tolerant of losing a copy. Missense variants: 512 observed, 739.62 expected, observed/expected ratio (o/e) 0.69, 90% interval 0.64 to 0.75. Synonymous variants: 234 observed, 283.24 expected, observed/expected ratio (o/e) 0.83, 90% interval 0.74 to 0.92.
Gene-disease validity (ClinGen):
ClinGen rates the evidence that SLC6A4 causes each of these diseases.
autism spectrum disorder (autosomal dominant): Disputed. A spectrum of developmental disorders that includes autism, and Asperger syndrome.
Homologues: Orthologues: chimpanzee SLC6A4 (99% identical), macaque SLC6A4 (99% identical), dog SLC6A4 (93% identical), pig SLC6A4 (93% identical), mouse Slc6a4 (93% identical), rabbit SLC6A4 (93% identical), rat Slc6a4 (92% identical), guinea pig SLC6A4 (85% identical), tropical clawed frog slc6a4 (76% identical), zebrafish slc6a4a (69% identical). Paralogues in human: SLC6A2 (48% identical), SLC6A3 (47% identical), SLC6A13 (40% identical), SLC6A11 (40% identical), SLC6A6 (40% identical), SLC6A12 (39% identical), SLC6A5 (39% identical), SLC6A8 (38% identical), SLC6A7 (38% identical), SLC6A9 (38% identical), SLC6A14 (37% identical), and 6 more.
Diseases named in the same sentence as SLC6A4 in open-access papers:
SLC6A4 is named in the same sentence as 241 diseases in open-access papers, as found by Europe PMC text mining. Sharing a sentence is not in itself a finding about the gene and the disease. The quoted sentences say what the papers report.
depression (467 papers, 2004 to 2026). "A meta-analysis conducted by Sharpley’s team confirmed the interaction of the 5-HTTLPR polymorphism within the promoter region of the 5-HTT (SLC6A4) gene with stressful life events and depression." (PMID 40416692, 2025). "SLC6A4 hypermethylation, together with the presence of the S allele, is linked toan increased risk of depression because SERT expression and serotonin uptake are reduced, especially in those with childhood adversity." (PMID 41234420, 2025). "The SLC6A4 gene is involved in regulating serotonin, which is essential for the effectiveness of antidepressants, and it has been linked to depression and epilepsy through various study designs." (PMID 40941042, 2025). "Deficiencies in serotonin 5-hydroxytryptophan (5-HT), a well-known feature of depression, are linked to variations in the SLC6A4 and HTR1A genes, which animal studies show can also increase seizure risk." (PMID 40941042, 2025). "Multiple studies have shown that high methylation of the SLC6A4 promoter region is significantly associated with an increased risk of depression." (PMID 40342516, 2025). "Specifically, SLC6A4 variants have been shown to moderate associations between adversity and physical development, behavior, and depression by increasing and decreasing risk for developmental outcomes according to the SLC6A4 variant." (PMID 39910899, 2025). "Genetic variants in the SLC6A4 gene exist in different individuals, and these variants are associated with an increased risk of posttraumatic stress disorder, depression, and obsessive–compulsive disorder." (PMID 40004189, 2025). "The relationship between genetic variants and depression severity or remission was also evidenced by findings involving SLC6A4, ABCB1, and HTR2A." (PMID 40725795, 2025). "Large-scale genetic studies consistently confirm SLC6A4 as a significant risk factor for major depression." (PMID 40941042, 2025). "The SLC6A4 polymorphism has also been associated with SSRI response to depression, and depressed patients with the SLC6A4 rs25531 LL genotype have been proven to respond better to fluoxetine than patients with other genotypes in the Indian population." (PMID 37581520, 2024). "Over-methylation of certain genes, such as BDNF, NR3C1, and SLC6A4, has been identified as a marker of increased susceptibility to depression." (PMID 39194576, 2024). "For example, epigenetic changes in the serotonin transport gene (SLC6A4) are associated with vulnerability to depression and treatment response." (PMID 39194576, 2024). "For example, the SLC6A4 gene (associated with depression) is in close proximity to “Vietnam veterans”, “mental health policies”, and “mushroom”." (PMID 39338085, 2024). "Variations in SLC6A4 have been linked to traits such as anxiety and depression, which are also associated with alcohol use disorder." (PMID 38491208, 2024). "Other epigenetic biomarkers of increased depression risk include hypermethylation of SLC6A4 and OTX genes." (PMID 34590201, 2023). "It is expected that alterations in the expression of SLC6A4 influence the serotonergic system and several studies have shown associations with methylation levels and psychiatric disorders, including depression and post-traumatic stress disorder." (PMID 36503539, 2022). "Clinical study results show that methylation of the SLC6A4 promoter is associated with increased susceptibility to depression, and higher SLC6A4 promoter methylation is significantly associated with childhood adversity." (PMID 35865627, 2022). "The first studied large-scale meta-analysis of research on depression suggested the statistically significant association of SLC6A4 and SLC6A3 genes among various genes of the monoaminergic system." (PMID 35456452, 2022). "Another study reported a strong positive correlation between level of SLC6A4 methylation, which is associated with depression, and FC in the amygdala in a healthy population." (PMID 35337298, 2022).
depression (continued). "For example, Hu conducted comparative genotyping of a case–control cohort and reported that a single nucleotide polymorphism, rs25531 in SLC6A4, likely impacts depression onset by interfering with the serotonin pathway." (PMID 35370858, 2022). "SLC6A4 is a serotonin transporter regulating serotonergic neurotransmission and is associated with depression." (PMID 36431060, 2022). "SLC6A4 is a serotonin transporter gene whose expression or methylation is strongly associated with the onset, phenotype, and prognosis of depression." (PMID 36507532, 2022). "A growing body of evidence suggests that the same trend is observed in the case of encoding for serotonin transporter SLC6A4 gene, which has been especially well-studied in the context of serotonergic signaling in depression." (PMID 33804455, 2021). "Candidate genes that undergo DNA methylation, such as brain-derived neurotrophic factor (BDNF), NR3C1 (encoding the glucocorticoid receptor), SLC6A4 (encoding the serotonin transporter), have been regarded as potential biomarkers of depression." (PMID 33815064, 2021). "In women, we found a significantly positive association of medium size between methylation factor 2 of SLC6A4 and depression severity (MADRS only)." (PMID 33765975, 2021). "Overall, our findings do not support the notion of a strong linear association between SLC6A4 regulation and depression." (PMID 33765975, 2021). "There are, however, ambiguous results regarding the association between SLC6A4 promoter methylation and depression severity." (PMID 33765975, 2021). "Beyond that, it is possible that SLC6A4 methylation was associated with depression severity at the time of onset of the first depressive episode." (PMID 33765975, 2021). "The association of DRD4 and SLC6A4 genetic polymorphisms with anxiety and depression in HD patients was also assessed after adjusting for demographic and clinical covariates." (PMID 33784353, 2021). "Their work demonstrated that carriers of the “short” allele in the promoter region (5-HTTLPR) of the SLC6A4 gene were more sensitive to the effects of stress on depression compared to those who were homozygous for the longer repeat allele." (PMID 34645846, 2021). "For instance, in patients with PSD the association of SLC6A4 methylation status with depression was significantly higher in participants carrying the 5-HTTLPR SS genotype." (PMID 33923526, 2021). "When looking at women and men separately, we found one significantly positive association between SLC6A4 methylation factor 2 and depression severity in women." (PMID 33765975, 2021). "This association is in line findings of higher SLC6A4 methylation being associated with depression severity." (PMID 33765975, 2021). "Our results suggest that BDNF or SLC6A4 genes profile methylation is independently associated with depressive disorders in patients with epilepsy." (PMID 34912196, 2021). "Lower average SLC6A4 methylation and lower CpG-2 methylation were weakly associated with less depression improvement after antidepressant treatment." (PMID 32012861, 2020). "Lower baseline ClpG-2 methylation of the SLC6A4 promoter was associated with increased clinical improvement in depression severity after eight weeks of treatment (r = −0.40; p = 0.04)." (PMID 32012861, 2020). "Three genes from the list (Slc17a7, Slc6a4 and Tph2) are associated with the terms abnormal fear/anxiety-related behavior and abnormal depression-related behavior." (PMID 32917038, 2020). "As such, SLC6A4 has previously been associated with a range of behavioral and psychiatric disorders including depression, OCD, anxiety and schizophrenia." (PMID 33198140, 2020). "Subgroup analyses showed that most studies found BDNF and SLC6A4 hypermethylations to be associated with MDD or depression in general." (PMID 30718449, 2019).